IL18 (interleukin 18)
Diseases named in the same sentence as IL18 in open-access papers (continued):
Sharing a sentence is not in itself a finding about the gene and the disease.
infection (continued). "In contrast, the attenuated NH/P68 presented a higher sensitivity to classical and IFN-α activation, and infection resulted in downregulated expression of MHC class I in all the subsets and release of IL-1α, IL-1β, and IL-18 from moM1." (PMID 32178332, 2020). "By contrast, the time courses of cytotoxicity, IL‐18 maturation, and GSDMD cleavage revealed that OspC3 prevented pyroptosis at 2 h post‐infection (Figs EV1C and EV5C)." (PMID 32657447, 2020). "The effector caspase-1 cleaves interleukin (IL)-1β, IL-18, and gasdermin D (GSDMD), resulting in cytokine release and the induction of pyroptotic cell death to eliminate infections and restore homeostasis." (PMID 32962268, 2020). "Thus, we determined whether local C5aR1 activation affects the transcription of IFN-γ (Ifng) in the spleen and brain as well as IL-12p35 (Il12a), IL-12p40 (Il12b), IL-18 (Il18), and iNOS (Nos2) in the brain of T. gondii-infected animals on day seven after infection using RT-qPCR." (PMID 32733463, 2020). "Neuroinflammation-related neuropeptide Y (NPY), IL-18, and MMP-14 showed distinct changes in the CSF and several brain regions (the prefrontal cortex, PVWM, and hippocampus) 24 h after infection." (PMID 31803186, 2019). "In contrast, infection with less-virulent HSV-1 clinical isolate KOS63 induce less activation of Caspase-1, IL-1β and IL-18." (PMID 31367214, 2019). "Collectively, these results indicate that the production of IL-18, while mediated by NLRP6 in the initial phase of infection, is then dependent on NLRC4, more than NLRP3." (PMID 31681274, 2019). "Other markers that were upregulated during the early active infection phase included IFN-γ, IL1-RA, IL-6, IL-10, IL-15, and IL-18; all of which have been reported in cases of human disease." (PMID 31557262, 2019). "Infection with influenza A virus induced the production of IFN-α/β, TNF-α, IL-1β and IL-18 in human peripheral macrophages." (PMID 30717382, 2019). "In combination with IL-12, IL-18 induces cell-mediated immunity following infection, and NK cells and certain T cells secret IFN-γ or type II IFN after stimulation with IL-18." (PMID 31426763, 2019). "Inflammation is normally induced during infection or tissue injury and can be tracked by increased levels of proinflammatory factors such as cytokines (IL6, IL8, IL18, and TNFa) in plasma samples." (PMID 31635416, 2019). "Because NO production is critical for intracellular killing, IL-18, an IFN-γ inducer, plays an important role in controlling infection." (PMID 30717382, 2019). "At 4 months after infection (T2), the dogs immunized with either salivary protein presented higher levels of IFN-γ, IL-6, IL-18, GM-CSF, IL-7, IL-15, TNF, and CCL2 when compared to controls." (PMID 30519235, 2018). "Beside IL-15 and IL-18, NK cell activation depends on IL-2 that is predominantly produced by activated CD4+ T cells during many infections." (PMID 30210499, 2018). "Increased levels of D-dimer, IL-6, sCD14, CXCL10, TNF-α, IL-18, and CCL2 among others have been shown to be increased during acute infection or chronically increased throughout infection." (PMID 29391069, 2018). "At T1, 2 months post-infection, the LM17- and LJL143-immunized dogs presented higher levels of IFN-γ, IL-6, IL-18, CXCL10, GM-CSF, IL-7, IL-15, and CCL2 in comparison to controls." (PMID 30519235, 2018). "Infection with Burkholderia pseudomallei or B. thailandensis triggers activation of the NLRP3 and NLRC4 inflammasomes leading to release of IL-1β and IL-18 and death of infected macrophages by pyroptosis, respectively." (PMID 29791511, 2018). "Significant changes of IFN-ɣ, IL-18 and CXCLi2 gene expressions were observed with NDV AF2240 infection at all different time points of infection." (PMID 28569155, 2017). "Instead, some cytokines involved in adaptive immune response activation (IL-18, IFN-γ) increased over the course of infection." (PMID 28290449, 2017).
infection (continued). "As we have previously reported, infection of Normal Human Bronchial Epithelial (NHBE) cells with human rhinovirus resulted in the release of significant levels of IL-1β and IL-18." (PMID 28830544, 2017). "In vivo experiments in chickens further confirmed the observed inflammatory and innate responses induced by vvIBDV in DT40 cells in vitro, and IL-1β, IL-18, TLR1, TLR2, and TLR3 are the predominant DE genes after vvIBDV infection." (PMID 28086922, 2017). "In our study, higher expressions of CXCLi2, IL-18 and IFN-γ were observed in infection by NDV AF2240, especially on day 3 post infection of the infected bursa correlating with the increased number of CD8+ T cells." (PMID 28569155, 2017). "At 3 h, the levels of il-18 and il-1β cytokine genes induced by PA14 wild-type infection of hCF were ~3-fold higher than the levels induced by PAO1 wild-type (P < 0.05)." (PMID 28469996, 2017). "We and others showed previously that IL-1α, IL-1β and IL-18 were increased in the lung of COPD patients and that these mediators were released by epithelial cells on infection with rhinovirus." (PMID 28830544, 2017). "Our findings demonstrated that the genetic deficiency of NLRP3, Casp1/11, and Asc totally impaired the expression of IL-1β, IL-18, NLRP3, Casp1, and ASC mRNA in the lungs of infected mice at week 4 of infection." (PMID 28740491, 2017). "Despite diminished levels of tumour-necrosis factor (TNF), IL-1β, IL-6, IL-12, IL-18 and MCP-1, and decreased neutrophil recruitment to the infection site, resistance to pulmonary tularaemia is increased." (PMID 28580947, 2017). "The highest levels of gene induction were observed 6 h after infection with wild-type PAO1 and PA14 strains, with significant increases at 3 h observed for il-18 and il-1β only with PA14 (P < 0.05)." (PMID 28469996, 2017). "During early infection (2wk), expression of pro-inflammatory cytokines IFN-γ, TNF-α, IL-17, IL-18, IL-22 (Th1 and Th17 responses) was negatively correlated with ANXA1 expression." (PMID 27484833, 2016). "SSM restrict their own infection and that of FRC through IFN-I, and possibly also other pro-inflammatory cytokines such as IL-18; and they recruit cellular effectors, including NK cells which kill infected FRC." (PMID 27926941, 2016). "Critically, on day 4 post-infection, IL-1β, TNFα, IL-6, CCL2 and CCL5 concentrations were significantly reduced in BAL fluid while IL-6 and IL-18 were reduced in the sera." (PMID 27283237, 2016). "The results demonstrate that the level of mRNA expression of IL-6, IL-8, IL-10, COX-2, IL-1β, IL-18, and TNF-α were significantly upregulated in peripheral blood monocytes following infection with H. parasuis for 3 or 6 h (p < 0.01)." (PMID 27502767, 2016). "On counter with such antigens, the complex interaction of antigen presenting cells, T cells and inflammatory mediators like IL1α, IL1β, TNFα, IL12, IL18 and IL23 lead to proinflammatory immune response and further clearance of infection." (PMID 27301453, 2016). "More precisely, the infection with HIV resulted in decreased IL-18BP concentrations and increased levels of biological active IL-18." (PMID 27821119, 2016). "The expression of the cytokines IL-18, IL-34 and chemokine CCL28 also increased following infection." (PMID 27677841, 2016). "Moreover, although the precise common γ chain cytokines available during primary and secondary infections may differ, their synergy with both IL-18 and antigen–antibody immune complexes underscores their contribution to NK cell activation during innate and adaptive responses." (PMID 27047490, 2016). "Processes related to cytoskeletal remodeling and cellular junctions, as well as inflammatory responses (IL-2, IL-5, IL-18, CCL2, TNF, IFN, and TGF-β signaling) were also upregulated following infection with C. concisus BAA-1457." (PMID 27677841, 2016).
infection (continued). "Infection of the mouse A/E pathogen C. rodentium has been shown to activate the NLRP3 inflammasome, which is critical for the production of IL-1β and IL-18 and protection in mouse macrophages." (PMID 26332984, 2015). "IL-18BP displays a high affinity for IL-18 (Kd 399 pM) and is present in the serum of healthy subjects at 20-fold molar excess to IL-18 to blunt the TH1 response to foreign organisms and reduce autoimmune responses to routine infection." (PMID 25699211, 2015). "The cytokines, IL1, IL18, IL6, IL12, and IL17, can interact with T cells to resist infection in humans and mice." (PMID 26369556, 2015). "Lastly, pattern "Yers-Salm" includes 1,694 genes whose expression levels changed preferentially after infection with Y. pseudotuberculosis or S. typhimurium (e.g. TLR8, TGFB1, IL18)." (PMID 26586179, 2015). "Serum proinflammatory cytokines were similar in both age groups, whereas significantly lower levels of IL-1beta, IL-18, IL-6, IL-12 and IL-15 were detected in the lungs of SARS-CoV-infected aged monkeys at either 5 or 10 days post infection." (PMID 24642138, 2014). "Chemokine C–C motif ligand (CCL2), IFN-γ, IL-12, IL-18, TNF-α, and transforming growth factor (TGF-β) confer protection during infection." (PMID 25339955, 2014). "Finally, to verify that increased inflammasome activation and IL-18 production were responsible for the lower bacterial numbers on day 7 or 10, we infected WT, Rip2−/−, and Rip2−/−×Il18−/− mice with C. rodentium and examined bacterial loads on day 7 after infection." (PMID 25254654, 2014). "In this study, expression levels of IL-4, IL-10, IL-13 and TNF-α were significantly up-regulated while the expression levels of IL-1β,IL-18,IFN-γ, IL-2, IL-15, IL-17F, IFN-α, IFN-β, IL-3 and CSF-1 were markedly decreased in PBMCs at all stages of infection." (PMID 24358317, 2013). "Having shown that infection of NHBE cells with HRV triggers the release of IL-1α, IL-1β and IL-18, we investigated the extent of the contribution of these cytokines to the release of other mediators by autocrine mechanisms." (PMID 23723976, 2013). "Infection with JEV for 3 h resulted in increased IL-1β and IL-18 mRNA levels in infected cells with respect to mock-infected condition." (PMID 22393394, 2012). "To analyze the possible role of the C12L gene, codifying for IL-18 bp, during MVA infection, we constructed an MVA with a deletion in the C12L gene, following the methodology described under Materials and Methods." (PMID 22384183, 2012). "After intraperitoneal amastigotes inoculation in wild-type and knockout mice for TNF-α, Nod2, Myd88, iNOS, IL-12p40, IL-18, CD4, CD8 and IFN-γ we found that the latter is crucial for controlling infection by G strain amastigotes." (PMID 22509418, 2012). "During the effector phase of the CD8 T cell response, at day 9 following infection, LCMV GP33-specific CD8 T cells from all of the cohorts analyzed produced IFN-γ in response to a brief (5.5 hr) exposure to IL-12+IL-18 and IL-12+IL-18+IL-21." (PMID 21980291, 2011). "Infection of mice with T. gondii elicits a dominant Th1 response involving interferon-gamma (IFN-γ), interleukin-12 (IL-12), IL-18, and tumor necrosis factor alpha (TNF-α)." (PMID 21957440, 2011). "Two or five days after MAb treatment (day 6 or 9 after infection), serum was harvested and levels of relevant cytokines (IFN-γ, TNF-α, IL-10, IL-12 p40, IL-17, and IL-18) were measured by bioplex assay." (PMID 22144897, 2011). "Lymphocytes from pooled salivary glands (D10 post-infection) and spleens (D2 post-infection) were then stimulated with anti-Ly49H, anti-NKG2D or IL-12/IL-18 for 6 hours." (PMID 21249177, 2011). "IL-18 is also a major IFN-gamma-inducing factor and both IL-18 and IFN-gamma act together in the host response to infection, but also in the pathogenesis of acute hepatic injury." (PMID 21569399, 2011). "Other cytokines that have been found to be important in control of MTb infection include TNF-α, IL-12(p40), IL-18 and IL-17." (PMID 20811496, 2010).
infection (continued). "The pathways leading to IFN-γ production during intracellular pathogen infection and following exposure to antigens that induce a TH1-type response favor IL-12 and IL-18 produced by macrophages and other cell types." (PMID 16396683, 2006). "CD4 T cells isolated after clearance of the acute infections or during the chronic phase of the LCMV Cl13 infection demonstrated a responsiveness to IL‐12 and IL‐18 stimulation by IFN‐γ production, regardless of their respective pathogen encounter." (PMID 40923840, 2025). "While ILC2s do not expand in CR-infected Il22-/- mice, injection of IL-18 into Il22-/- mice at 2- and 3-days post CR infection triggered ILC2s expansion." (PMID 40591723, 2025). "In addition, 25–100 mg/kg baicalin reduced the mRNA expression levels of IL-1β, IL-6, IL-8, IL-18, TNF-α, and COX-2 in the spleen compared to the infection group (p < 0.05)." (PMID 40427533, 2025). "While IL-33 and IL-18 have been shown to play a role in CR infection, it is not known if they signal to colonic lamina propria ILC2s." (PMID 40591723, 2025). "Our results showed that IL-18 is essential for the control of infection because the absence of this cytokine results in a severe infection." (PMID 40315193, 2025). "Furthermore, the IL-1β, IL-18, and LDH levels in bronchoalveolar lavage fluid (BALF) from WT mice increased in a dose-dependent manner 7 days after MPXV infection." (PMID 41225161, 2025). "The predominance of caspase-8 (without releasing IL-1β and IL-18) reshapes inflammatory responses and cell death mechanisms during infection." (PMID 41208996, 2025). "Notably, inflammasome scores (based on IL1B, IL18, NLRP3, GSDMD, PYCARD) remained stable in YG CMs and IMs during infection but increased consistently in AG subsets from 4 to 6 dpi." (PMID 40794649, 2025). "Notably, myeloid cells in AG ferrets showed significantly elevated expression of inflammatory cytokines, including IL-1β, IL-10, IL-18, NFκB1, and S100A8, as well as upregulated IFNGR2 expression throughout infection, especially 4dpi." (PMID 40794649, 2025). "LTA -+252 and CCC, TNFA-308 and CCC, IL10-819 rs1800871 and CCC, TLR4 haplotype D229G/T399I with protection from CCC, TIRAP S180L (rs8177374) and rs8177376 (strong linkage disequilibrium) with CCC, IL18 rs360719 and infection, IL17A rs4711998 and infection, TGFB1+10 rs1800470 with infection." (PMID 40297326, 2025). "Among the polymorphisms associated in one cohort which were tested in different cohorts but where the association was not replicated, we have IL18 rs2043055 with CCC, IFNG rs2430561 and infection, IL4 −590 and infection, TGFB1 −509 rs1800469 and infection." (PMID 40297326, 2025). "Additionally, inflammatory markers such as IL18 and IFNG demonstrate differential expression, with increased activity in certain infection states, reflecting their role in modulating inflammation in response to ROS." (PMID 39770656, 2024). "When the piglets were injected with baicalin and probenecid, the IL-1β, IL-10, IL-18, TNF-α and IFN-γ mRNA levels decreased compared to those in the infection group (p < 0.01), which suggested that baicalin and probenecid inhibited cytokine production in piglets infected with G. parasuis." (PMID 39075542, 2024). "Furthermore, quercetin significantly decreased the expression levels of Il-6, Il-8, Il-18 and Tnf-α, compared to the GPS infection group (p < 0.05)." (PMID 38927100, 2024). "In addition, 25–100 mg/kg baicalin attenuated the changes in IL-1β, IL-10, IL-18, TNF-α and IFN-γ mRNA expression compared to that in the infection group (P < 0.01)." (PMID 39075562, 2024). "ART suppression of viremia, however, failed to reduce IL-18 levels below those observed during the acute phase of infection beyond the initial control at 3 months of ART." (PMID 39201388, 2024). "Nevertheless, IFN-γ signaling on Cx3cr1+ cells was not required to promote IL-18 release during infection." (PMID 39446964, 2024).
infection (continued). "To determine the mRNA expression levels of IFN-γ, TNF-α, IL-1β, and IL-18, as well as the abundance of cytokines IFN-γ, TNF-α, IL-6, and IL-10 in the kidneys of uninfected and PbA-infected mice at day 7 post-infection, we performed quantitative real-time PCR and CBA assays, respectively." (PMID 38787228, 2024). "Also, for IL-18 and caspase-1, there is a statistically significant reduction comparing WT THP-1 and KO THP-1 cells after infection with Lt-P10." (PMID 38707903, 2024). "p. i, but it induced lower levels of IL-1β, IL-18, and GSDMD-NT, which led to an alleviated inflammatory infiltration and pathological damage in the lungs and brains, and a lower death rate compared with wild-type PRV strain infection." (PMID 39316625, 2024). "Notably, quantification of IL-18 release from the ceca of WT and Il22−/− mice revealed severely reduced levels in Il22−/− mice under both PBS-treated and S. Typhimurium-infection conditions." (PMID 39428744, 2024). "In the triple-depletion model presented here, we found that treatment with M-T807R1/Clodrosome prior to infection resulted in an augmented inflammatory signature, as indicated by increased plasma IL-1β, IFN-γ, IL-10, IL-6, and IL-18 levels in the WT-infected animals." (PMID 38668247, 2024). "Due to the amplification effect of proinflammatory cytokines such as interleukin (IL)-8 and IL-18, MRMP infection might elicit a persistent and intense immune response, with LDH being considered a more sensitive immunological marker than CRP." (PMID 39143259, 2024). "Plasma cytokines (IL-1β, IL-3, IL-6, IL-8, IL-18, IP-10, MIG, TNF-α, IFN-γ, MIP-1α and MIP-1β) and total peroxide (TPX) levels were quantified at baseline and at months 1 and 6 after the onset of the infection." (PMID 37894054, 2023). "Together with the enhanced macrophage release of IL-18 following infection with T, M1 M2 but not with WT-TRC conidia, these results suggest the role of PIG1 in conidia survival upon macrophage interaction, rather than the direct involvement of melanin." (PMID 36836250, 2023). "Another report suggests that infection induces neutrophils pyroptosis via ATP-mediated P2X7R signaling, resulting in cytoplasmic low K+ activation of NLRP3 inflammasome together with mature IL-1β and IL-18 release." (PMID 37063905, 2023). "Additionally, pro-inflammatory cytokines, including MIF, PAI-1, IL-18, CXCL1, CXCL12 and IL-8, were statistically decreased (P < 0.05) in 10−6 M 1α,25(OH)2D3-pretreated A549 cells by 12 h post-infection." (PMID 36758060, 2023). "In contrast, prior work has observed that primary human keratinocytes express a high level of pro-IL-18 and release it in their resting state without infection or further stimulation." (PMID 37068092, 2023). "In contrast, BMDMs deficient in NLRC4 had no cell death and significantly reduced IL-18 release in response to these infections." (PMID 37557956, 2023). "Therefore, the innate response to in vitro infection of macrophages with both LAMV and WT MeV includes production of IL-6 and TNFα and activation of the NLRP3 inflammasome to release IL-1β and IL-18." (PMID 36851476, 2023). "As expected, inflammasome activation in response to Δ6 Yptb infection is T3SS dependent, as an isogenic Yptb strain cured of its virulence plasmid encoding the T3SS did not induce IL-18 release in human IECs." (PMID 37615436, 2023). "However, during infection with SpeB-expressing GAS, there was activation of IL-18 signaling and production of and a proportionate SpeB-dependent increase in the production of IFN-γ." (PMID 37068092, 2023). "However, stimulation of NK cells with IL-12 + IL-18 induced KLRG1 and resulted in Eomes downregulation, implying that some inflammatory cytokines produced upon infection can reduce Eomes expression and functional capacity of NK cells." (PMID 37828009, 2023).